ICAM1 (intercellular adhesion molecule 1)
Diseases named in the same sentence as ICAM1 in open-access papers (continued):
Sharing a sentence is not in itself a finding about the gene and the disease.
osteosarcoma (continued). "We determined that AREG increases the expression of intercellular adhesion molecule-1 (ICAM-1) through PI3K/Akt signaling pathway via its interaction with the epidermal growth factor receptor, thus resulting in the enhanced cell migration of osteosarcoma." (PMID 26503469, 2015). "Moreover, like its upstream regulator, PI3K, Akt regulates the AREG-induced cancer cell migration of osteosarcoma and the expression of ICAM-1 at treatment with an Akt inhibitor (Akti), can inhibit the AREG-induced migration and ICAM-1 up-regulation." (PMID 26503469, 2015). "To test whether AREG increased the cell migration of osteosarcoma through EGFR, we reduced the EGFR expression by transfecting EGFR siRNA and found that EGFR siRNA inhibited the AREG-induced cancer cell migration and inhibited the AREG-induced ICAM-1 upregulation of the mRNA level." (PMID 26503469, 2015). "Although ICAM-1 has also been shown to play roles during the initiation of the metastatic cascade driving tumor progression, this development seems to not involve the CXCL1-triggered metastatic cascade in osteosarcoma cells." (PMID 34760697, 2021). "In conclusion, the results presented here indicate that demethylating treatment with DAC against osteosarcoma cells can lead to an obvious enhancement in expression of CTAs, which may be brilliant targets for adoptive immunotherapy; while MHC-I and ICAM-1 were not changed." (PMID 25301731, 2014).
lupus (21 papers, 2006 to 2025). "This is consistent with a previous report of elevated levels of Icam1 from the aorta of lupus mice when compared with healthy control mice." (PMID 39337408, 2024). "Previous reports have shown that the lupus CD11b allele reduces cell adhesion to several CR3 ligands, including ICAM-1, under static and/or flow conditions." (PMID 23451151, 2013). "Consistent with our observations, lupus-prone MRL-Faslpr/lpr (MRL/lpr) mice lacking ICAM-1 or lymphocyte function-associated antigen-1 showed amelioration of glomerulonephritis, which was correlated with a decrease in neutrophil accumulation in the glomeruli." (PMID 32655553, 2020). "This fits with lupus mouse model studies which show that although local VCAM-1 expression is elevated in lupus-affected organs, ICAM-1 is more critical for transendothelial migration of leukocytes into inflamed tissues." (PMID 26746423, 2016). "Moreover, the novel potent PAR2 antagonist punicalagin significantly ameliorated kidney injury and splenomegaly and reduced the expression of intercellular adhesion molecule 1 (ICAM-1) and vascular adhesion molecule 1 (VCAM-1) in NZB/W F1 lupus mice." (PMID 40002827, 2025). "We, therefore, utilized a pristane-induced lupus mouse model to dissect whether activated CD4+ T cells from pristine-treatment mice promoted B cell activation and differentiation in the MHC and ICAM-1-dependent manners." (PMID 35095344, 2022). "Besides, it is also reported that JKAP limits T cells overproducing ICAM‐1 and VCAM‐1 in the kidney of systemic lupus erythematosus patients." (PMID 35274367, 2022).
type 1 diabetes (21 papers, 2006 to 2025). "We genotyped one ICAM1 SNP (G241R; rs1799969), which has previously been associated with type 1 diabetes." (PMID 18045485, 2007). "The intercellular adhesion molecule-1 (ICAM-1) gene is located on chromosome 19p13, which is linked to Type 1 diabetes (T1D)." (PMID 16978373, 2006). "ICAM-1 expression has been reported to be increased in vascular endothelial cells of pancreatic islets of NOD mice as well as in humans with new-onset type 1 diabetes." (PMID 38115297, 2023). "ICAM-1, the best characterized cell surface adhesion molecule, has been shown to be involved in the pathogenesis of type 1 diabetes by participating in the extravasation of circulating leukocytes into the inflamed pancreas." (PMID 38115297, 2023). "We did not obtain any evidence of an association between type 1 diabetes and either ICAM1, IL12B or TBX21, all of which had previously been associated with type 1 diabetes." (PMID 18045485, 2007). "Interestingly, our EC model showed an increase in CXCL10, ICAM1, IL-6, and MIF, which are associated with type I diabetes development." (PMID 31835296, 2019). "TAF5L, PDCD1, TCF7, IL6 and ICAM1 may be amongst the numerous loci with small effects in type 1 diabetes." (PMID 18045485, 2007). "Serum levels of soluble intercellular adhesion molecule 1 (sICAM-1) and GDF15 were also higher in participants with type 1 diabetes." (PMID 41285865, 2025). "The present study investigates the differences between subgroups of children with type 1 diabetes who differ in LDL cholesterol levels, higher pulsation index in large elastic and muscular arteries, and higher ICAM-1 or sVCAM–1 levels." (PMID 40564977, 2025). "Moreover, the shared enrichment of ICAM1 and CXCL12 in Type 1 diabetes pathways suggests that these genes may exacerbate the onset and progression of PD in diabetic patients." (PMID 41377896, 2025). "Paediatric patients with type 1 diabetes, but without signs of CD, had increased expression of MHC class II antigens and intercellular adhesion molecule 1 (ICAM-1) on the intestinal epithelium." (PMID 24871322, 2014).
endotoxemia (20 papers, 2004 to 2025). "For example, the intercellular adhesion molecule 1 (ICAM-1)/CD54 level was enhanced in the endothelia during inflammation in murine models of endotoxemia." (PMID 39768040, 2024). "Regarding the immune response, Plat+ capillary-1 are engaged in the innate immune response through interaction with neutrophils via ICAM-1 adhesion during endotoxemia." (PMID 38348045, 2024). "Functionalization of dexamethasone-loaded dextran nanogels with ICAM-1 recognizing antibody increased their lung accumulation in LPS-induced endotoxemia mice model and blocked the overexpression of proinflammatory molecules VCAM-1 and ICAM-1 in lungs lysates." (PMID 27703301, 2016). "Our study showed that ICAM-1 levels increased at 24 h and declined at 48 h during endotoxemia." (PMID 38348045, 2024). "Plat+ capillaries are involved in the innate immune response through their interaction with neutrophils via ICAM-1 adhesion during endotoxemia, while Cd74+ capillaries epxressed high level of MHC proteins play a role in adaptive immune response through their interaction with T cells." (PMID 38348045, 2024). "Thus, inflammatory markers, IL-6, ICAM 1 and endotoxemia, show significantly higher values in pediatric obese patients, leading to chronic and systemic inflammation." (PMID 33924229, 2021). "Moreover, inflammatory markers, IL-6, ICAM 1 and endotoxemia were significantly higher in obese patients versus the control group." (PMID 33924229, 2021). "Finally, we identified and verified 9 key genes (Cd274, Cxcl1, Cxcl9, Icam1, Ifit2, Isg15, Stat1, Tlr2, and Usp18), and we predicted seven potential drugs for multi-organ damage in LPS-induced endotoxemia." (PMID 33330617, 2020). "Ameliorated PMN recruitment to brain tissue has been demonstrated during endotoxemia in ICAM-1-deficient mice, similar to our findings in which an anti-ICAM-1 antibody reduced PMN adhesion to hCMEC/D3, suggesting an important role for β2-integrin-ICAM-1 interactions in PMN adhesion to CMEC." (PMID 25882865, 2015). "In parallel, PC treatment effectively blocked leukocyte recruitment and improved survival of WT mice and Icam-1-deficient mice in LPS-induced endotoxemia, but failed to do so in RAGE-deficient mice." (PMID 24876676, 2014). "The intravenous administration of PDTC had partial therapeutic effects on endotoxemia-induced lung tissue edema and damage, neutrophil influx to the lung, alveolar-capillary barrier dysfunction, and high systemic levels of TNFa and ICAM-1 as well as over-activation of NF-κB." (PMID 21569464, 2011). "Next, we studied whether RAGE and ICAM-1 are linked to the anti-inflammatory PC pathway in more disease relevant mouse models: LPS-induced acute lung injury (LPS-ALI) and LPS-induced lethal endotoxemia." (PMID 24876676, 2014). "Furthermore, two independent groups have demonstrated that ICAM-1 plays a pivotal role in neutrophil activation and aggregation, highlighting its involvement in increased adherence and aggregation upon exposure to inflammatory factors also in a murine model of endotoxemia." (PMID 39910535, 2025). "Adhesive factors such as intercellular adhesion molecule 1 (ICAM1) and vascular cell adhesion molecule 1 (VCAM1) are scarcely expressed in the intact endothelium but are up-regulated by endotoxemia and facilitate the recruitment of inflammatory cells." (PMID 38550779, 2024). "Adhesion of iRBCs to CD36 and ICAM-1 as well as rosetting was similar in children with or without endotoxemia." (PMID 26830671, 2016).
injury (19 papers, 2012 to 2025). Damage inflicted on the body as the direct or indirect result of an external force, with or without disruption of structural continuity. "Adhesion molecules, such as ICAM-1 and P-selectin, have been associated with poor outcomes of acute lung injury." (PMID 36119052, 2022). "In conclusion, low serum melatonin level and high ICAM-1 level in patients with HICH were found to be related to the degree of brain injury and are influencing factors of poor prognosis in HICH patients." (PMID 37492282, 2023). "In the setting of lung ischemia-reperfusion injury, ICAM 1 expression had a biphasic pattern of early downregulation and a late-phase upregulation." (PMID 32309444, 2020). "Biomarkers of endothelial and alveolar epithelial injury, such as von Willebrand factor (vWF) and soluble intercellular adhesion molecule-1 (ICAM-1), have been associated with pathogenesis and outcome of patients with acute lung injury." (PMID 30359446, 2018). "Our results suggest a novel role of ICAM-1 in the regulation of inflammation and raise a possibility that targeting ICAM-1/miR-124/MCP-1 axis in modulating inflammation during acute lung injury." (PMID 29340098, 2017). "The interaction of endothelial cell including PMVEC and neutrophil is very complicated whilst the firm neutrophil - PMVEC adhesion is the key step of progression of acute lung injury and mainly mediated by ICAM-1." (PMID 23527096, 2013). "It has previously been shown that blocking ICAM-1 results in improved neurological scores following brain injury, possibly due to reduced PMN recruitment." (PMID 22269349, 2012). "Targeting ICAM-1 and downstream miR-124 may present a new therapeutic strategy for acute lung injury." (PMID 29340098, 2017). "Specifically, we found that PIMT attenuates LPS-stimulated endothelial activation and acute lung injury by inhibiting NF-κB signaling through methylation of TRAF6 and inhibition of N-glycosylation of the cell surface adhesion molecule ICAM-1." (PMID 37070640, 2023). "Skin injury activates adhesion molecules VCAM-1 and ICAM-1 in endothelial cells, and triggers the subsequent release of chemokines and inflammatory cell infiltration." (PMID 35335455, 2022). "The expressions of ICAM-1 and VCAM-1 have been reported to be increased in toxic and BD-induced models of acute lung injury but remained unchanged in the present study as reported by other authors." (PMID 28753621, 2017).
Arthritis (18 papers, 2008 to 2024). Inflammation of a joint. "ICAM‐1 binds to the ligand lymphocyte functional antigen‐1, which induces inflammatory cell aggregation and promotes arthritis." (PMID 37786887, 2022). "ICAM-1 plays a role in pathological processes including inflammation, arthritis, cardiovascular diseases, and eye diseases." (PMID 25675437, 2015). "In arthritis, the increased expression of ICAM-1 results in the migration of leukocytes to the joints." (PMID 24490631, 2014). "We previously demonstrated alterations in the sCD18 complexes in the blood and synovial fluid of patients with arthritis and the ability of sCD18 to inhibit leukocyte binding to ICAM-1." (PMID 24490631, 2014). "Intercellular adhesion molecule-1 (ICAM-1) is another potential target for imaging of arthritis as it was demonstrated to be expressed on synovial endothelial cells and mice deficient in ICAM-1 showed a reduction in arthritis incidence and severity." (PMID 25099015, 2014). "Further, baseline IL-6 and ICAM-1 levels significantly correlated with the number of joints with active arthritis at baseline (r = 0.37, p = 0.0059; r = 0.32, p = 0.0096; respectively)." (PMID 20822542, 2010). "We previously demonstrated alterations in sCD18 complexes in the blood and synovial fluid of patients with arthritis and showed that sCD18 binding to ICAM-1 could be an anti-inflammatory regulatory mechanism in the immune system." (PMID 24490631, 2014). "In addition, the inhibition of the interaction between LFA-1 and ICAM-1 may induce the occurrence of arthritis in patients with PSO, possibly altering the balance of leucocyte extravasation." (PMID 37520537, 2023). "Aortic vascular mRNA expressions of IL-6 and CXCL-1 were positively correlated while ICAM-1 and VCAM-1 negatively correlated with arthritis score and with radiographic score." (PMID 35488311, 2022). "ICAM-1 and CXCL-1 expression increased in AIA rats at the preclinical phase and at the onset of arthritis while VCAM-1 increased only at the onset of arthritis." (PMID 35488311, 2022). "The swollen joint count (SJC) was identified, among which ICAM-1 and CCL18 were reported relevant to synovial tissue in RA, whereas VEGFD was proposed to participate in the pathogenesis of arthritis." (PMID 34869404, 2021). "In the placebo + MTX group, changes in ICAM-1 and CRP levels were significantly correlated with the number of joints with active arthritis at week 14 (r = 0.64, p < 0.0001; r = 0.38, p = 0.004; respectively) (data not shown)." (PMID 20822542, 2010). "By reducing neutrophil recruitment and production of the inflammatory cytokines, BCA attenuated the development of zymosan-induced arthritis in mice, which correlates with the lower expression of adhesion molecules (VCAM-1, ICAM-1, and E-selectin) in neutrophils treated with BCA in vitro." (PMID 33995086, 2021). "In conclusion, recruitment of leukocytes into the joints and the ensuing arthritis in the K/BxN STA model seem to be dependent on the expression of LFA-1 on leukocytes, especially neutrophils, and the binding to its ligands, ICAM-1, ICAM-2, and JAM-A, expressed on the activated vascular endothelium." (PMID 27313578, 2016). "The present study revealed that increased mRNA expression of adhesion molecules (ICAM-1) and CXCL-1 (IL-8) occurred as early as at the preclinical phase of AIA and reached its maximum at the onset of arthritis (ICAM-1, VCAM-1, IL-8) without any changes at the acute inflammatory phase." (PMID 35488311, 2022). "Induction of arthritis in HO-1−/− mice but not in HO-1+/− animals significantly increased serum levels of MMP-3, PAI-1, E-selectin and ICAM-1 whereas VEGF levels were lower than those of HO-1+/+ or HO-1+/− mice." (PMID 23285041, 2012). "Moreover, blockade of LFA-1 with an anti-LFA-1 mAb reduced the already ongoing inflammation, and functional blockade of its counter-receptors, ICAM-1, ICAM-2, and JAM-A, provided a reduction, but not complete amelioration, of arthritis." (PMID 27313578, 2016).
lung fibrosis (18 papers, 2005 to 2025). "ICAM-1 deficiency ameliorates lung fibrosis induced by intratracheal bleomycin administration." (PMID 24516598, 2014). "The levels of soluble intercellular adhesion molecule-1 (sICAM-1) have been reported to increase in patients with idiopathic pulmonary fibrosis." (PMID 26543791, 2015). "Another study demonstrated that ICAM-1 levels were significantly higher in dcSSc patients and were correlated with the presence of contracture of phalanges, pulmonary fibrosis, joint involvement, and increased erythrocyte sedimentation rate." (PMID 24516598, 2014). "In pre-clinical studies, Pirfenidone altered TGF-β transcription in a murine model of bleomycin-induced pulmonary fibrosis, IL-6 expression in rat models of acute pulmonary inflammation, and expression of ICAM-1 in cultured human fibroblasts." (PMID 17540023, 2007). "Furthermore, we found a strong positive correlation between ICAM1 + EVs and well-known mediators of SSc lung fibrosis (IL6 and VEGF) within both ILD and PF-ILD subgroups." (PMID 40370719, 2025). "Nevertheless, similar to infections with Schistosoma spp., prolonged ICAM-1 upregulation in foxes could contribute to lung fibrosis." (PMID 40529303, 2025). "In fact, ICAM1 may amplify the inflammatory process, and implement the progression to fibrosis as shown in the model of bleomycin induced lung fibrosis." (PMID 40370719, 2025). "However, in an ICAM-1 knockout mice, bleomycin has been reported to induce a more severe pulmonary fibrosis compared to their wild-type counterparts." (PMID 16159396, 2005). "IL-17 also appears to be directly involved in the pathogenetic events leading to lung fibrosis 10 and it is well known that IL-17 can regulate the release of cytokines involved in fibrosis development, such as CTGF, TGFβ and ICAM-1 in several tissues 24,25." (PMID 35693738, 2022). "A group of eight proteins has recently been propose as disease progression serum markers in Idiopathic Pulmonary Fibrosis (IPF): KL-6, surfactant protein A, and MMP-7, CCL-18, S100A12, IL-8, ICAM-1 and VCAM-1." (PMID 24216293, 2013). "In comparison to the neutrophilic cases, the IPA analysis of the proteomic datasets derived from horses with metachromatic inflammation revealed enrichment in pathways related to hypersensitivity reaction (CD44, ICAM1, SOD1, PSAP, CDH1) and lung fibrosis (AGER, TGFBR2, FBLN1, S100A9)." (PMID 39594673, 2024). "STAT1 antisense oligonucleotides (ASON) could inhibit the secretion of TNF-α and ICAM-1 in alveolar macrophages (AMs), and STAT1 could become a target of treating pulmonary fibrosis." (PMID 33072088, 2020). "The current in vitro PCLS model revealed several differences to experimental animal models of chronic injury, where during the course of disease, for example in pulmonary fibrosis, a number of AEC I specific proteins are strongly diminished: T1α, ICAM-1, aquaporin-5, RAGE and Cav-1." (PMID 25635824, 2015). "Also the fact that membrane-bound ICAM-1 regulates the Src kinases activity, which controls the RhoA/ROCK/MLC2 signaling pathway, is in accordance with previous data suggesting a role for Src in fibroblast contractility and during kidney and lung fibrosis." (PMID 27901489, 2017). "Moreover, even after adjusting for IL6, VEGF, and CRP, ICAM1 + EVs remained an independent predictive factor of ILD progression, indicating that ICAM1 + EVs could be a crucial proinflammatory/profibrotic signal pathway in lung fibrosis." (PMID 40370719, 2025).